MRGPRX1 (MAS related GPR family member X1)
Description:
G protein-coupled receptor specifically expressed in sensory neurons of dorsal root ganglion, and which is involved in itch perception and pain transmission. Specifically activated by a variety of enkephalin (PENK) neuropeptides, such as BAM22 and BAM8-22, which induce itch in a histamine-independent manner. Activated by some tick defensins, such as I.persulcatus Def1 and I.ricinus Def2, evoking itch. Also activated by conotoxin CNF-Tx2, inducing itch sensation. Activated by the antimalarial drug chloroquine; however, activation requires concentrations that exceed the chloroquine concentrations observed in plasma of patients undergoing chloroquine treatment. Also activated following cleavage by the dust mite cysteine protease Der p1. Ligand binding causes a conformation change that triggers signaling via guanine nucleotide-binding proteins (G proteins) and modulates the activity of downstream effectors, such as adenylate cyclase. MRGPRX1 is both coupled to G(q) and G(i) G proteins: G(q) coupling activates phospholipase C-beta, releasing diacylglycerol (DAG) and inositol 1,4,5-trisphosphate (IP3) second messengers, leading to sensitize TRPV1 in pruriceptors, while G(i) coupling mediates inhibition of adenylate cyclase activity. Activation of MRGPRX1 in the peripheral nervous system elicits itch, evoking scratching. MRGPRX1 activation in sensory neurons of the nasal mucosa mediates sneezing responses to irritants or influenza-virus (By similarity). Activation in the central nervous system dampens chronic pain: BAM8-22-binding at the central terminals prevents pain signals passing to spinal cord neurons, attenuating spinal nociceptive transmission. Activation by CXCL17 induces chemotactic movement.
Synonyms: MRGX1; SNSR4; GPCR; MGRG2
Tractability: Small molecule: a structure with a bound ligand is known; a high-quality ligand is known; it belongs to a druggable protein family. Antibody: UniProt places it where antibodies can reach, with medium confidence; UniProt predicts a signal peptide or a membrane-spanning region; its Gene Ontology location is reachable by antibodies, with medium confidence. PROTAC: a small molecule that binds it is known.
Target class: Family A G protein-coupled receptor; Membrane receptor
Chemical probes: ML 382
Gene: Protein-coding gene on chromosome 11 (18,933,499 to 18,939,414, reverse strand). Ensembl gene ENSG00000170255.
Subcellular location: Cell membrane
Gene Ontology:
Molecular function: C-C chemokine receptor activity; G protein-coupled receptor activity; transmembrane signaling receptor activity
Biological process: adenylate cyclase-inhibiting G protein-coupled receptor signaling pathway; cell migration; cell surface receptor signaling pathway; chemokine-mediated signaling pathway; negative regulation of sensory perception of pain; phospholipase C-activating G protein-coupled receptor signaling pathway; response to chloroquine; sensory perception of itch; signal transduction; G protein-coupled receptor signaling pathway; sneeze reflex; adenylate cyclase-modulating G protein-coupled receptor signaling pathway
Cellular component: cell surface; plasma membrane; membrane
Genetic constraint (gnomAD): Loss-of-function variants: 0 observed, 0.59 expected, observed/expected ratio (o/e) 0, 90% interval 0 to 1.82. That is too few expected variants to judge how well the gene tolerates losing a copy. Missense variants: 411 observed, 389.33 expected, observed/expected ratio (o/e) 1.06, 90% interval 0.97 to 1.14. Synonymous variants: 208 observed, 171.43 expected, observed/expected ratio (o/e) 1.21, 90% interval 1.08 to 1.36.
Homologues: Orthologues: chimpanzee MRGPRX1 (96% identical), macaque MRGPRX1 (86% identical), rabbit MGRG2 (57% identical), dog MRGPRX (56% identical), mouse Mrgprx1 (52% identical), mouse Mrgprx2 (52% identical), mouse Mrgpra9 (51% identical), rat Mrgprx1 (51% identical), rat Mrgprx3 (51% identical), mouse Mrgpra1 (50% identical), mouse Mrgprb2 (50% identical), rat Mrgprb4 (49% identical), and 16 more. Paralogues in human: MRGPRX3 (83% identical), MRGPRX4 (79% identical), MRGPRX2 (66% identical), MRGPRD (38% identical), MAS1L (34% identical), MRGPRF (32% identical), MAS1 (32% identical), MRGPRE (32% identical), MRGPRG (30% identical), GPR152 (23% identical).
Diseases named in the same sentence as MRGPRX1 in open-access papers:
MRGPRX1 is named in the same sentence as 7 diseases in open-access papers, as found by Europe PMC text mining. Sharing a sentence is not in itself a finding about the gene and the disease. The quoted sentences say what the papers report.
itch (6 papers, 2019 to 2026). "Although the present study suggests that BAM8-22 and MRGPRX1 are involved in the mechanism underlying cholestatic pruritus, other mediators may still be involved." (PMID 31350433, 2019). "Of these, the MRGPRX receptors (MRGPRX1-4) are primarily expressed in humans and held to induce pruritus." (PMID 37555911, 2023). "Adding to this, the antimalarial drug chloroquine induces severe pruritus in some individuals via MRGPRX1 activation." (PMID 36385768, 2022). "Recently, a study revealed that human MrgprX1 and mouse MrgprA3 play pivotal roles in CQ-induced pruritus using Mrgpr-cluster△−/− mice." (PMID 36430803, 2022). "MRGPRA3 and MRGPRC11 are mouse orthologs of human MRGPRX1, and MrgprA3 is also activated by CQ, resulting in CQ-induced pruritus." (PMID 36430803, 2022). "Mrgprs play a pivotal role in somatosensation, including itch and pain, and recently, it has been reported that MrgprX1 functions as a receptor for CQ and plays an essential role in CQ-induced pruritus, such as in the activation of small DRG neurons." (PMID 36430803, 2022). "It is recently reported that MRGPRX1 mediates CQ-induced itch in humans." (PMID 37347749, 2023). "Also, MRGPRC11 (referred to as mouse MRGPRX1) expression increases in mouse DRG neurons in a cholestasis itch model based on bile acid production." (PMID 36385768, 2022). "Moreover gain- and loss-of-function research on utilizing neurons in Mrgpr-cluster△−/− DRG strongly suggests the potential of MrgprX1 as a therapeutic target to modulate CQ-induced pruritus." (PMID 36430803, 2022). "Specifically, both increased action of BAM8-22 in the skin and enhanced sensitivity of MRGPRX1 in the sensory neuron may augment pruritus, which in turn leads to enhanced scratching behaviour in BDL mice." (PMID 31350433, 2019).
cholestasis (2 papers, 2019 to 2022). Impairment of the bile flow caused by obstruction within the liver, or outside the liver in the bile duct system. "Fittingly, sensory neurons from those mice showed increased Ca2+-influx in response to the endogenous MRGPRX1/C11 agonist BAM8-22, which was also found to be upregulated in skin of cholestasis itch mice compared to controls." (PMID 36385768, 2022). "More importantly, treatment with skin homogenate of BDL mice increased intracellular calcium level in Mrgprx1/HeLa cells, strongly suggesting that BAM8-22 could be a pruritogen responsible for cholestasis." (PMID 31350433, 2019). "MRGPRX1 could play a role in cholestatic itch as well, both genes for MRGPRC11 (rodent analog of MRGPRX1) and proenkephalin, the precursor of the endogenous MRGPRX1-ligand bovine adrenal medulla peptide 8-22 (BAM8-22), are upregulated in a cholestasis mouse model." (PMID 36385768, 2022).
allergic asthma (1 paper, 2024). A asthma with a basis in a pathological type I hypersensitivity reaction. "Der p1, a cysteine protease and major allergen of house dust mites, induces the release of the pro-inflammatory cytokine IL-6, in part through activation of MRGPRX1, suggesting that MRGPRX1 is potentially involved in neuroinflammatory mechanisms in AR and allergic asthma." (PMID 39185421, 2024). "Thus, MRGPRX1 antagonists may hold therapeutic value in treating AR and allergic asthma." (PMID 39185421, 2024).
Allergy (1 paper, 2021). An allergy is an immune response or reaction to substances that are usually not harmful. "Activation of the Mas-related GPCR X1 (MRGPRX1) by Der p1, a major allergen from house dust mite, may contribute to allergy and inflammation." (PMID 34721374, 2021).
breast carcinoma (1 paper, 2020). "IQSEC3 and MRGPRX1 are tumor-related genes and were first discovered in this study as a new prognostic marker for breast cancer." (PMID 33170908, 2020).
MRGPRX1 also shares sentences with these, for which no sentence is quoted: atopic dermatitis (1 paper); tumor (1).